ADAMTSL3 (ADAMTS like 3)
Synonyms: ADAMTSL-3; KIAA1233; punctin-2
Tractability: Antibody: UniProt places it where antibodies can reach, with high confidence; UniProt predicts a signal peptide or a membrane-spanning region; its Gene Ontology location is reachable by antibodies, with medium confidence.
Gene: Protein-coding gene on chromosome 15 (83,653,683 to 84,039,842, forward strand). Ensembl gene ENSG00000156218.
Subcellular location: Secreted, extracellular space, extracellular matrix
Subcellular location (Human Protein Atlas): Vesicles; Predicted to be secreted
Pathways (Reactome):
Disease: Defective B3GALTL causes PpS
Metabolism of proteins: O-glycosylation of TSR domain-containing proteins
Gene Ontology:
Molecular function: protein binding
Biological process: extracellular matrix organization
Cellular component: elastic fiber; extracellular matrix
Genetic constraint (gnomAD): Loss-of-function variants: 115 observed, 193.92 expected, observed/expected ratio (o/e) 0.59, 90% interval 0.51 to 0.69. The upper end of that interval is the gene's LOEUF score, 0.69, which puts it in group 2 of 6, group 1 being the genes least tolerant of losing a copy. Missense variants: 1,907 observed, 2,117.3 expected, observed/expected ratio (o/e) 0.9, 90% interval 0.87 to 0.94. Synonymous variants: 702 observed, 754.47 expected, observed/expected ratio (o/e) 0.93, 90% interval 0.87 to 0.99.
Homologues: Orthologues: chimpanzee ADAMTSL3 (99% identical), macaque ADAMTSL3 (97% identical), dog ADAMTSL3 (87% identical), rabbit ADAMTSL3 (87% identical), mouse Adamtsl3 (85% identical), pig ADAMTSL3 (85% identical), rat Adamtsl3 (85% identical), guinea pig ADAMTSL3 (85% identical), tropical clawed frog adamtsl3 (62% identical), zebrafish adamtsl3 (50% identical). Paralogues in human: ADAMTSL1 (44% identical), ADAMTS7 (17% identical), ADAMTS9 (16% identical), ADAMTS12 (16% identical), ADAMTS20 (16% identical), ADAMTS13 (14% identical), ADAMTS16 (14% identical), ADAMTS18 (13% identical), THSD4 (13% identical), ADAMTSL2 (12% identical), ADAMTS6 (12% identical), PAPLN (12% identical), and 13 more.
Diseases named in the same sentence as ADAMTSL3 in open-access papers:
ADAMTSL3 is named in the same sentence as 31 diseases in open-access papers, as found by Europe PMC text mining. Sharing a sentence is not in itself a finding about the gene and the disease. The quoted sentences say what the papers report.
colorectal cancer (5 papers, 2015 to 2025). A primary or metastatic malignant neoplasm that affects the colon or rectum. "In Koo BH’s study, identification of frequent ADAMTSL3 mutations in colorectal cancer suggested it might have a regulatory role in cellular homeostasis in colorectal epithelium or in pathways to colorectal malignancy." (PMID 28865443, 2017). "The protein encoded by ADAMTSL3 (A Disintegrin And Metalloproteinase with TromboSpondin Like 3) is involved with extracellular matrix function and to cell–matrix interactions, and is frequently mutated and under-expressed in colorectal cancer." (PMID 28193203, 2017). "Recently, frequent mutations in ADAMTSL3 have been identified recently in colorectal cancer." (PMID 26462029, 2015). "Adamtsl3 secreted from presynapses binds to the transmembrane protein DCC (Deleted in Colorectal Cancer) and controls its synaptic localization, which is required for the maintenance of GABAergic synapses in the adult brain." (PMID 41036704, 2025).
schizophrenia (4 papers, 2009 to 2022). A major psychotic disorder characterized by abnormalities in the perception or expression of reality. "ADAMTSL3 encodes a glycoprotein that localizes to the extracellular matrix, belongs to a family of metalloproteases, and is proposed to be a candidate gene for schizophrenia, with proposed function in synaptogenesis." (PMID 32400971, 2020). "To assess more formally the combined evidence of association for the ADAMTSL3 SNPS we extended the Bayesian framework developed by Wakefield to consider the cumulative posterior odds for the hypothesis of true association with schizophrenia, as data from successive datasets are added." (PMID 19197363, 2009). "While our genome-scan identified no definitive associations between SNPs and schizophrenia risk, SNPs in the ADAMTSL3 gene were the most strongly associated." (PMID 19197363, 2009).
heart failure (3 papers, 2022 to 2024). Inability of the heart to pump blood at an adequate rate to meet tissue metabolic requirements. "ADAMTSL3 levels were increased in heart biopsies from patients with heart failure and our studies in mice demonstrate an important role of ADAMTSL3 for cardiac function and survival." (PMID 36539599, 2022). "In the present study, we investigated regulation of ADAMTSL3 in biopsies from patients with heart failure, and its role in cardiac remodelling after AB-induced LV pressure overload in L3-KO and WT littermate mice." (PMID 36539599, 2022). "In line, ADAMTSL3 is cardio-protective and improves survival in mouse heart failure." (PMID 38324186, 2024). "Indeed, Adamtsl3-/- mice subjected to experimental heart failure by pressure overload develop exacerbated contractile dysfunction and cardiac dilatation with increased mortality." (PMID 38324186, 2024). "ADAMTSL3 levels increase in human and mouse heart failure, suggesting a role in cardiac function." (PMID 38324186, 2024). "In experimental heart failure, ADAMTSL2 and ADAMTSL3 are interesting candidates for in vivo overexpression, either as a transgenic mouse model, or via viral injections." (PMID 38324186, 2024).
diabetes (2 papers, 2020 to 2023). "ADAMTSL3 is a candidate gene for diabetes, which is, in turn, a risk factor for IA." (PMID 32095376, 2020).
meningioma (2 papers, 2017 to 2024). A generally slow growing tumor attached to the dura mater. "Of the two mutations in the grade I meningioma, one (EPHB3) mutation was verified by Sanger sequencing, and of the nine mutations in the grade II tumor, two (CAPN5 and ADAMTSL3) were verified by Sanger sequencing." (PMID 28193203, 2017). "In addition, we identified two candidate driver genes, CAPN5 and ADAMTSL3, which could contribute to the elevated growth rate of the grade II meningioma." (PMID 28193203, 2017). "Further study of ADAMTSL3 and CAPN5 may lead to elucidation of their molecular implications in meningioma pathogenesis." (PMID 28193203, 2017).
abdominal aortic aneurysm (1 paper, 2024). Enlargement and ballooning of the vessel that supplies arterial blood to the abdomen, pelvis and legs. "ADAMTSL3 variants are enriched in patients with intracranial aneurysms, and ADAMTSL3 expression is reduced in both intracranial and abdominal aortic aneurysms." (PMID 38324186, 2024).
Alzheimer disease (1 paper, 2009). A progressive, neurodegenerative disease characterized by loss of function and death of nerve cells in several areas of the brain leading to loss of cognitive function such as memory and language. "We then confirmed a causal relationship between rs950169 and the observed splicing pattern using a MINIGENE system, and showed an association between rs950169 genotype and the splice form of ADAMTSL3 in brain tissue from both healthy controls and Alzheimer's disease patients." (PMID 19197363, 2009).
aortic stenosis (1 paper, 2022). Aortic valve stenosis is a aortic valve disease caused by the incomplete opening of the aortic valve. "ADAMTSL3 expression was upregulated 2-fold in LVs of patients with aortic stenosis (AS), and in the myocardium of patients with ischemic DCM (iDCM), ADAMTSL3 mRNA and protein were upregulated 1.5-fold." (PMID 36539599, 2022).
cardiac hypertrophy (1 paper, 2022). "To understand the role of ADAMTSL3 in response to LV pressure overload, we performed RNA-seq analysis on LVs one week post-AB, when both genotypes showed cardiac hypertrophy, but only L3-KO hearts were dilated." (PMID 36539599, 2022).
Inguinal hernia (1 paper, 2022). Protrusion of the contents of the abdominal cavity through the inguinal canal. "Pathway analyses identify several genes with a strong link to collagen and/or elastin (ADAMTS6, ADAMTS16, ADAMTSL3, LOX, ELN) in the vicinity of associated loci for inguinal hernia, which substantiates an essential role of connective tissue morphology." (PMID 35680855, 2022).
medulloblastoma (1 paper, 2022). A malignant, invasive embryonal neoplasm arising from the cerebellum. "Worth noting is that the ADAMTSL3--SH3GL3 circular fusion is also found in medulloblastoma, along with two other ADAMTSL3--SH3GL3 circular fusions encompassing the same SH3GL3 exon and one SH3GL3--ADAMTSL3 circular fusion encompassing the same ADAMTSL3 exon." (PMID 35804907, 2022).
osteoarthritis (1 paper, 2025). A noninflammatory degenerative joint disease occurring chiefly in older persons, characterized by degeneration of the articular cartilage, hypertrophy of bone at the margins and changes in the synovial membrane. "LOF + MIS variants in ADAMTS6, SPRY2 and COLGALT2 are protective against osteoarthritis, whereas aggregation of these variants in ADAMTSL3, VIT, IL11 and THBS3 confer risk of osteoarthritis." (PMID 40205036, 2025).
tumor (5 papers, 2015 to 2024). "In agreement with previous studies, we observed decreased ADAMTSL3 expression in tumors compared with adjacent non tumor tissues and low ADAMTSL3 expression was associated with a worse prognosis." (PMID 33805340, 2021). "ADAMTSL3 was identified as a tumor suppressor gene since down-regulation of ADAMTSL3 is associated with poor overall survival and predicted poor relapse-free survival." (PMID 33805340, 2021). "Importantly, the mutations in CAPN5 and ADAMTSL3 were detected by WES in all four fragments of grade II tumor and were verified by Sanger in all four fragments as well, suggesting that these mutations were likely present in the cell undergoing fast clonal expansion." (PMID 28193203, 2017). "The 8 SNPs (CD3EAP rs967591, TNFRSF10B rs1047266, AKT1 rs3803300, C3 rs2287845, HOMER2 rs1256428, GNB2L1 rs3756585, ADAMTSL3 rs11259927, and CD3D rs3181259) were found to be significantly associated with OS and/or DFS when adjusted for age, gender, smoking status, tumor histology, pathologic stage." (PMID 26462029, 2015).
cancer (3 papers, 2021 to 2023). A tumor composed of atypical neoplastic, often pleomorphic cells that invade other tissues. "ARHGAP21, a negative regulator of cancer cell growth, migration, and invasion, and ADAMTSL3, essential for the development and growth of lymphatic vessels, have been reported to have increased methylation levels in high-Gleason-score PCa in African Americans." (PMID 37895233, 2023). "ADAMTSL3, which has been proven to involve in cell proliferation in cancer, was only mutated in the ATP5B-high group." (PMID 34122507, 2021). "The proliferative role of ADAMTSL3 has been described in different human cancers." (PMID 37895233, 2023).
cardiac disease (1 paper, 2022). "The role of ADAMTSL3 in heart pathology and cardiac disease is investigated with Adamtsl3-deficient mice using CRISPR-Cas9 gene editing." (PMID 36539599, 2022). "In future investigation, this possibility could be addressed by increasing ADAMTSL3 levels experimentally in models of heart disease, to reveal potential cardioprotective effects." (PMID 36539599, 2022).
ADAMTSL3 also shares sentences with these, for which no sentence is quoted: arachnodactyly (1 paper); attention deficit-hyperactivity disorder (1); autism spectrum disorder (1); bipolar disorder (1); cardiomyopathy (1); connective tissue disorder (1); emphysema (1); generalized anxiety disorder (1); hip osteoarthritis (1); Hypertension (1); hypertrophic cardiomyopathy (1); intracranial aneurysms (1); metabolic syndrome (1); obsessive-compulsive disorder (1); sarcopenia (1); unipolar depression (1).